IL13 (interleukin 13)
Diseases named in the same sentence as IL13 in open-access papers (continued):
Sharing a sentence is not in itself a finding about the gene and the disease.
echinococcosis (1 paper, 2024). A parasitic infection caused by tapeworm larvae of Echinococcus. "Interestingly, unlike the type of T cell response generated in chronic patients with echinococcosis, we found that primed splenocytes with HF-stimulated BMDCs blocked the induction of cytokines related to Th2 profile (il-4, il5, il-13)." (PMID 38817444, 2024).
endometrial cancer (1 paper, 2020). Primary or metastatic malignant neoplasm involving the endometrium (mucous membrane that lines the endometrial cavity). "A third smaller, but distinctly separate, network of IL13, IL21, ANKAR, CAPS, and IGFALS was associated with Wnt and VEGF signaling, and are likely associated with environmental cues in high-grade endometrial cancer." (PMID 32471032, 2020). "Activated CD8+ TIL in endometrial cancer barely produced IL-13 (1.06%), but they did produce GM-CSF (median 26.08%) and, to a lesser extent, IL-21 (median 8.79%) and very little IL-10 (median 3.7%)." (PMID 32471032, 2020).
endometrial tumors (1 paper, 2021). "The concentration of IP-10, PDGF-AA, TGFα, fractalkine, IL-1α, IL-15, IL-13, sCD40L, VEGF, PDGF-BB, IL-17, RANTES, IL-1Ra and IL-8 trended higher in CM from endometrial tumors than that measured in CM from adjacent non-cancerous tissue." (PMID 33968059, 2021).
enteropathy (1 paper, 2016). "In contrast, the SG−/− mice display aggravated enteropathy despite low levels of IL-13 suggesting that other serglycin-dependent mediators overrule the effects of lowered IL-13 levels." (PMID 27267469, 2016). "Furthermore, the increased enteropathy, the reduced inflammatory cytokine levels, the altered IL-4 and IL-13 levels, and increased IgE levels suggest that serglycin proteoglycans have a regulatory role in the immune response during T. spiralis infection." (PMID 27267469, 2016).
eosinophilic bronchiectasis (1 paper, 2023). A bronchiectasis inflammatory endotype characterized by elevated blood eosinophils (≥300 cells/μL) or sputum eosinophils (≥3%), associated with type 2 (Th2) inflammation, elevated fractional exhaled nitric oxide (FeNO), and IL-5/IL-13 signaling. "Previous studies have suggested that IL-13–driven mucus hypersecretion could be a key mechanism in eosinophilic bronchiectasis." (PMID 37780108, 2023).
eosinophilic leukemia (1 paper, 2011). "In vitro treatment of the GM-CSF stimulated eosinophilic leukemia cell line (EoL-1) cells with LXA4 inhibited secretion of IL-8, IL-13, and eotaxin suggesting this molecule may have negative feedback implications on IL-13 mediated pathways." (PMID 23283176, 2011).
eosinophilic pneumonia (1 paper, 2023). An inflammatory lung disorder characterized by an increased number of eosinophils in the lungs. "Eosinophilic pneumonia (EP) is a rare but noteworthy adverse effect linked to dupilumab, an interleukin-4 (IL-4) and IL-13 inhibitor used in the managing atopic diseases." (PMID 38259470, 2023).
erythroderma (1 paper, 2025). "Erythroderma is considered a Th2‐type cytokine dominant condition, and IL‐4 and IL‐13 are implicated to play important roles in the etiology of erythroderma." (PMID 39526626, 2025). "The etiology of erythroderma is suggested to be a Th2‐dominant condition with IL‐4/IL‐13 playing a central role, suggesting that therapies targeting those Th2 molecules may result in sufficient effects." (PMID 39526626, 2025). "Therapies targeting Th2 type molecules, IL‐4 and IL‐13, may be expected for refractory erythroderma, although such therapies should be applied to idiopathic erythroderma after malignancies are excluded." (PMID 39526626, 2025).
esophageal tumor (1 paper, 2018). "By contrast, the esophageal tumor size and serum levels of IL-1β, IL-4, IL-13 and tumor necrosis factor-alpha (TNF-α) were not significantly affected by adding açaí to the diet for 35 weeks." (PMID 29966007, 2018).
Eustachian tube obstruction (1 paper, 2024). "Therefore, by reducing IL-4 and/or IL-13 levels, Dupilumab may inhibit periostin production, thus suppressing inflammation, and consequently improving Eustachian tube obstruction." (PMID 39595049, 2024).
fibromyalgia (1 paper, 2021). A chronic disorder of unknown etiology characterized by pain, stiffness, and tenderness in the muscles of neck, shoulders, back, hips, arms, and legs. "For instance, T helper 2 (Th2) anti-inflammatory cytokines, including IL-4, IL-5 and IL-13, have been reported to decrease in fibromyalgia patients, whereas inflammatory cytokines IL-6 and IL-8 are found to elevate in fibromyalgia, indicating a potential role in the chronic pain of fibromyalgia." (PMID 33912165, 2021).
Flavivirus Infections (1 paper, 2025). Infections with viruses of the genus FLAVIVIRUS, family FLAVIVIRIDAE. "Both species exhibited a balanced immune response, with TNF-α and IL-1β playing key roles in inflammation, while IL-10 and IL-13 were prominent in immunomodulation—patterns that are consistent with other flavivirus infections." (PMID 40143314, 2025).
gallbladder cancer (1 paper, 2022). "Interestingly, inhibitory effects of IL4 and IL13 in human gallbladder cancer cells have hardly been investigated so far." (PMID 35207737, 2022).
ganglionitis (1 paper, 2014). "In contrast, IL13 was significantly increased and there was a tendency towards increased expression of IL1β (P = 0.055) in the ganglionitis subgroup in the older (>110 days) BB-DP animals." (PMID 25354336, 2014).
gastric disease (1 paper, 2022). "IL-13 is thought to be produced by Th2 cells, but macrophages, mast cells, and ILC2s are also capable of producing IL-13, as observed in mouse models of gastric disease." (PMID 35757757, 2022).
gastric polyps (1 paper, 2024). "Through bidirectional investigation approach, it could be inferred that certain biomarkers are more likely to be found later in the course of the illness, like bNGF, FGFBasic, GCSF, GROa, IL-13, IL-5, IL-7, MCSF, SCGFb in gastric polyps, and CTACK, MIF in colonic polyps." (PMID 39439893, 2024).
gastric tumor (1 paper, 2023). "Because of the limited antigenicity of the gastric tumors in gp130F/F mice and our inability to detect IL13- or IL25-responsive MDSCs in these tumors, we cannot exclude an indirect contribution of IL25 signaling via MDSCs or IL13 produced by T cells to GC development." (PMID 37898600, 2023). "To explore whether these in vitro dependencies of gastric tumor organoids could translate to therapeutic approaches in vivo, we treated tumor-bearing gp130F/F mice with α-IL13 or α-IL25 neutralizing antibodies." (PMID 37898600, 2023). "Together this data leads us to conclude that gastric tuft cells and ILC2s, like their intestinal counterparts, are the primary source of IL25 and IL13 during SPEM and gastric tumor development." (PMID 37898600, 2023).
gastric ulcer (1 paper, 2023). An ulcerated lesion in the mucosal surface of the stomach. "This study indicates that IL-13 is induced in IDM-induced small intestinal mucosal injury with ulceration, suggesting that there may be a different mechanism underlying the pathogenesis of IDM-induced small intestinal mucosal injury than that of gastric ulcer." (PMID 37834420, 2023).
glomerulosclerosis (1 paper, 2012). A hardening of the kidney glomerulus caused by scarring of the blood vessels. "NWT-03 and VIL both reduced renal interleukin (Il)-1β/Il-13 mRNA expression and glomerulosclerosis." (PMID 23071636, 2012).
Graves disease (1 paper, 2014). Graves' disease is an autoimmune disorder that leads to overactivity of the thyroid gland (hyperthyroidism).It is caused by an abnormal immune system response that causes the thyroid gland to produce too much thyroid hormones. "This could be explained with IL-13 stimulation of B cells to secrete TBII, TSAb, and IgE in Graves' disease patients." (PMID 24959371, 2014).
heroin addicts (1 paper, 2021). "The analysis revealed that the levels of IL-1ra, IL-1β, IL-5, IL-12p70, IL-13, IL-15, MIP-1β, bFGF, and RANTES in the plasma of heroin addicts in the AW and PW stages were not significantly different from those in the plasma of the control group subjects (data not shown)." (PMID 34489980, 2021).
herpes infections (1 paper, 2025). "Notably, no herpes infections or serious AEs were observed, consistent with other reports that highlight the low immunosuppressive risk associated with IL-13 inhibition." (PMID 40869553, 2025).
Herpes simplex infection (1 paper, 2022). "We found that the most significantly enriched pathway (ranked by p-value) for the LC response cluster was Herpes simplex infection; other significant GO terms were involved in the immune response, such as defense response to virus and response to interleukin-13." (PMID 35990259, 2022).
histoplasmosis (1 paper, 2021). A disease caused by the fungus Histoplasma capsulatum. "Significant differences in the median values of IL-1β, TNF-α, IFN-γ, IL-18, IL-17A, IL-33, IL-13, and CXCL8 were reached in all the groups studied, suggesting that these cytokines play a role in the inflammatory processes associated with histoplasmosis and pneumocystosis." (PMID 34829225, 2021). "Significant differences in median values of SP-A, IL-1β, TNF-α, IFN-γ, IL-18, IL-17A, IL-33, IL-13, and CXCL8 were found among all the groups studied, suggesting that these cytokines play a role in the local inflammatory processes of histoplasmosis and pneumocystosis." (PMID 34829225, 2021).
Hydrocephalus (1 paper, 2023). Hydrocephalus is an active distension of the ventricular system of the brain resulting from inadequate passage of CSF from its point of production within the cerebral ventricles to its point of absorption into the systemic circulation. "Both DCX and GPC2 associated with hydrocephalus, NSE, IL-1β, IL-2, IL-8, IL-13." (PMID 36800341, 2023). "Significant, positive associations were found for both CSF-DCX and CSF-GPC2 respectively, with hydrocephalus, NSE, IL-2, IL-8, IL-13, and IL-1β." (PMID 36800341, 2023).
Hyperkalemia (1 paper, 2025). An abnormally increased potassium concentration in the blood. "The reduction in IL-13 efficacy during [K+]e supplementation seen here in BV2 cells indicates that microglia are responsive to hyperkalemia." (PMID 40956452, 2025). "We demonstrated in vitro that extrinsic factors including pro-inflammatory signals, ECM deposition, acidosis, excessive glutamate release and hyperkalemia all contribute to this effect, reducing the efficacy of IL-13 in forcing M2-like polarisation in BV2 and miPSC-microglia." (PMID 40956452, 2025).
hypertriglyceridemia (1 paper, 2018). A laboratory test result indicating elevated triglyceride concentration in the blood. "For instance, a recent work demonstrated that PBMC show increased IL-13 expression in type 2 diabetic nephropathy patients that also exhibit hypertriglyceridemia." (PMID 29675435, 2018).
hypothyroidism (1 paper, 2023). Abnormally low levels of thyroid hormone. "Conversely, when we treated hypothyroidism as an exposure factor, we detected a causal association between hypothyroidism and 13 inflammatory cytokines (IL-13, IL-16, IL-2rα, IL-6, IL-7, IL-9, G-CSF, SCGF-β, IP-10, MIG, MIP-1β, SDF-1α, and TNF-α)." (PMID 38317717, 2023).
IgG4-related diseases (1 paper, 2022). "In IgG4-related diseases, IL-13-positive mast cells are increased, and IgE-positive mast cells, rather than T cells, release cytokines such as IL-4 and IL-10." (PMID 35888006, 2022).
infarction (1 paper, 2013). A localised pathological necrosis of tissue resulting from obstruction of the blood supply usually by a thrombus, an embolus, or vascular torsion. "The neurobehavioral scores, infarction volumes, and the levels of IL-1β and IL-13 were detected." (PMID 23970940, 2013).
intestinal parasite infection (1 paper, 2019). "A major driver of the ILC2 response following intestinal parasite infection has been identified as the tuft cell, which produces IL-25 promoting ILC2 expansion and IL-13 production." (PMID 31730667, 2019).
IPEX syndrome (1 paper, 2023). "By our knowledge, this is the first report of IPEX syndrome successfully treated by antiIL-4/IL-13 therapy." (PMID 36713411, 2023).
iron deficiency anaemia (1 paper, 2010). "While levels of TNF, IFN-γ and IL-1β (type I) and IL-10 and IL-13 (type II) seemed decreased in iron deficiency anaemia, the levels of IL-12 and IL-5 appeared increased." (PMID 20546583, 2010). "This seems supported by weak evidence of similar interaction in the same direction when examining the influence of iron deficiency anaemia on the association between IFN-γ and IL-5, and between IFN-γ and IL-13." (PMID 20546583, 2010).
Jaundice (1 paper, 2022). Yellow pigmentation of the skin due to bilirubin, which in turn is the result of increased bilirubin concentration in the bloodstream. "Stratified analyses by disease severity uncovered that elevated plasma levels of IL-7, eotaxin, IP-10, and IL-13 were significantly associated with the presence of unfavorable outcomes including jaundice, fibrosis, and PH in BA patients." (PMID 35452452, 2022). "Compared with BA patients with non-jaundice, the patients with jaundice had significantly increased plasma levels of 3 anti-inflammatory cytokines including IL-ra (P = 0.002), IL-4 (P = 0.010), and IL-13 (P<0.001)." (PMID 35452452, 2022).
Kawasaki disease (1 paper, 2022). A rare inflammatory disease characterized by an acute febrile, systemic, self-limiting, medium-vessel vasculitis primarily affecting children. "In our previous research we have found that patients with Kawasaki disease had higher levels both M1 related cytokine TNF-α, and the M2 related cytokines IL-6, IL-4 and IL-13 in the acute phase of Kawasaki disease, which decreased after IVIG therapy." (PMID 35154107, 2022).
keratoconjunctivitis (1 paper, 2017). Inflammation of both the cornea and the conjunctiva. "However, ILC2, like T cells (Th2 cells), may play a role in keratoconjunctivitis in IL33tg mice, as ILC2 can produce massive IL-5 and IL-13 in response to the stimulation of IL-334, and those Th2 cytokines are produced by ILC2 in the corneas of IL33tg mice." (PMID 28855579, 2017).
kidney cancer (1 paper, 2023). Primary or metastatic malignant neoplasm involving the kidney. "Additionally, our research found that the interleukin-4 and interleukin-13 signalling pathways, which affect immune cell activity and are related to inflammation and kidney cancer, are enriched." (PMID 37481674, 2023).
laryngeal carcinoma (1 paper, 2024). Carcinoma that arises from the laryngeal epithelium. "This study showed differences, especially in the level of cytokines (IL-4, IL-13 and IL-10), depending on the model of direct and indirect interactions between laryngeal cancer cells and macrophages." (PMID 39057050, 2024).
left ventricular dilation (1 paper, 2019). "Interestingly, in contrast to the IL-13−/− female mice, IL-13−/− male mice exhibit a significant higher mortality and increased left ventricular dilation compared with WT mice after MI." (PMID 30761134, 2019).
leiomyoma (1 paper, 2021). A well-circumscribed benign smooth muscle neoplasm characterized by the presence of spindle cells with cigar-shaped nuclei, interlacing fascicles, and a whorled pattern. "Major cytokines, namely the expression of interleukin 1 (IL1), 6 (IL6), 11 (IL11), 13 (IL13), 15 (IL15), 33 (IL33), tumor necrosis factor α (TNFα), and the granulocyte-macrophage colony-stimulating factor, have been implicated to leiomyoma pathophysiology." (PMID 34442017, 2021). "Numerous studies described leiomyoma cells exhibiting a significantly greater expression of IL1, IL4, IL5, IL6, IL10, IL11, IL13, and IL15." (PMID 34442017, 2021).
lichen sclerosus (1 paper, 2024). "The response of vulvar lichen sclerosus to dupilumab may indicate that the IL-4/IL-13 signaling pathway plays a role in the pathogenesis of lichen sclerosus." (PMID 38988357, 2024). "Although previous studies have shown the presence of Th1 activity in the labia lichen sclerosus, further research is needed to elucidate the potential role of Th2 and IL-4/IL-13 cytokines in vulvar and nonvulvar lichen sclerosus." (PMID 38988357, 2024).
lower respiratory tract infection (1 paper, 2021). "SNPs in genes coding for interleukin (IL)-8, IL-19, IL-20, IL-13 mannose-binding lectin, interferon-gamma, and a regulated on activation, normal T cell expressed and secreted polymorphism have been associated with subsequent wheeze after RSV lower respiratory tract infection in term-born infants." (PMID 34386467, 2021).
lupus nephritis (1 paper, 2019). Glomerulonephritis in the context of systemic lupus erythematosus. "Thus, the aim of this research is to determine the plasma levels of IL-25 and Th2-associated cytokines (IL-4, IL-5, IL-6, IL-9, IL-10, IL-13) in SLE patients with (SLE-LN) and without lupus nephritis." (PMID 31697750, 2019).
magnesium deficiency (1 paper, 2010). A nutritional condition produced by a deficiency of magnesium in the diet, characterized by anorexia, nausea, vomiting, lethargy, and weakness. "Magnesium deficiency was associated with an 80% increase in IL-13 concentrations, and seemed associated with a 49% increase in IL-5 concentrations." (PMID 20546583, 2010). "Magnesium deficiency, on the other hand, was associated with an increase in production of IL-13 by 80%; 95% CI: 31% to 371% and a reduction in IFN-γ production." (PMID 20546583, 2010). "Magnesium deficiency was associated with an increase in the concentration of IL-13 among type II cytokines." (PMID 20546583, 2010). "IL-13 is also believed to regulate immunoglobulin switching from IgG isotype to IgE, this is particularly important because it signifies that prolonged magnesium deficiency may predispose individuals to hypersensitivity reactions." (PMID 20546583, 2010).
membranous nephropathy (1 paper, 2014). "On the other hand, the IgG4 isotype related to Th2 cells stimulated by IL-13 and IL-40 is strongly associated with proliferative and crescent forms, as well as paraneoplastic membranous nephropathy." (PMID 25580314, 2014).
mononucleosis (1 paper, 2022). "This indicates that patients with stomach pain, bloating, and symptoms of an irritable bowel at baseline, severe gastrointestinal symptoms when they contracted mononucleosis, and low levels of IL-13 and/or IL-5 at baseline had nearly an 80% chance of developing severe ME/CFS six months following IM." (PMID 35350440, 2022).
morbid obesity (1 paper, 2024). An excess of body weight, normally defined as an individual with a body mass index greater than 35 or a body weight greater than one hundred percent of ideal body weight. "The multiple linear regression model results reveal a significant relationship between hepatic levels of ACE and the cytokines IL-4 and IL-13 in patients with morbid obesity and MASLD." (PMID 39337863, 2024). "Moreover, we observed increased hepatic IL-13 expression in patients with morbid obesity, MASLD, and SAH compared to those without SAH." (PMID 39337863, 2024).
mucormycosis (1 paper, 2022). "Activation of the IL-4/IL-13 pathway was previously shown to play an important role in air-way hyperactivity associated with allergen-induced hypersensitivity, a condition characteristic of mucormycosis." (PMID 35387075, 2022).
mucous membrane pemphigoid (1 paper, 2022). Mucous membrane pemphigoid is a bullous dermatosis characterized clinically by blistering of the mucous membranes followed by scarring, and immunologically by IgG, IgA and/or C3 deposits on the epidermal basement membrane. "Additionally, IL-13 exerts profibrotic and proinflammatory effects on the human conjunctival fibroblasts by up-regulating the expression of the T cell co-stimulatory molecules CD80, CD40, and CD154, suggesting a significant role in the pathophysiology in mucous membrane pemphigoid (MMP)." (PMID 35140724, 2022).